EGFR (epidermal growth factor receptor)
Diseases named in the same sentence as EGFR in open-access papers (continued):
Sharing a sentence is not in itself a finding about the gene and the disease.
lung adenocarcinoma (continued). "Oncogenes were detected in 64% of lung adenocarcinomas, while available information in relation to EGFR, BRAF, KRAS, ALK, ROS1, and MET gene mutations in lung adenocarcinomas are growing steadily." (PMID 34708154, 2021). "EGFR-mutated lung adenocarcinoma with metastasis over the right clavicle resulting in a pathological fracture was diagnosed according to the result of the incisional biopsy." (PMID 33640029, 2021). "The data suggest that the presence of VM has a negative impact on the response to treatment and survival of lung adenocarcinoma with common EGFR mutations." (PMID 33549061, 2021). "The probability of EGFR‐sensitive mutations in Chinese patients with advanced lung adenocarcinoma is about 50%." (PMID 33438349, 2021). "Genetic alterations found in lung adenocarcinomas are clinically important, and EGFR mutations and translocations involving ALK, ROS and RET genes are currently targets for therapy." (PMID 34625038, 2021). "Epidermal growth factor receptor (EGFR) gene in lung adenocarcinoma is associated with good clinical response to EGFR-tyrosine kinase therapy." (PMID 34181354, 2021). "Especially for Asian patients, our previous study more than half of patients with lung adenocarcinoma harbored EGFR kinase domain mutations." (PMID 33954108, 2021). "An additional work reported successful determination of EGFR mutations (exons 18–21) by RTqPCR and direct sequencing in 136 lung adenocarcinoma patients." (PMID 34199799, 2021). "Studies by Nose and colleagues demonstrated that strong ERβ nuclear expression was implicated in the manifested EGFR mutations, in turn resulting in its favorable prognostic significance being influenced by EGFR mutations in lung adenocarcinoma patients." (PMID 35008242, 2021). "The relationship between lung adenocarcinoma subtype and lymph node involvement, EGFR mutation and KRAS mutation was also evaluated." (PMID 34026636, 2021). "The aim of the present study was to investigate and compare the treatment efficacy of afatinib, erlotinib, and gefitinib according to EGFR mutation type in patients with lung adenocarcinoma." (PMID 33430803, 2021). "In this study, the rate of EGFR mutation-positive findings in cases of lung adenocarcinoma was 75%, higher than in the general population." (PMID 33550544, 2021). "This study aims to compare the prevalence of EGFR mutation status in bronchoalveolar lavage and peripheral blood referring to the gold standard - tissue biopsy in patients with primary lung adenocarcinoma." (PMID 34040898, 2021). "T790M mutation has been reported to cause therapeutic resistance to first‐ or second‐generation TKIs in approximately 49% of EGFR mutant‐associated lung adenocarcinomas." (PMID 33586356, 2021). "Older data showed that ever-smokers with EGFR-mutated lung adenocarcinoma tend to be diagnosed with more advanced pathologic stage disease." (PMID 33435440, 2021). "In the lung adenocarcinoma patients with the EGFR L858R mutation, the WWOX rs3764340 G genotype or rs73569323 T genotype of WWOX was shown to be associated with a significantly increase of primary tumor size and invasion of adjacent tissues." (PMID 34948746, 2021). "T790M mutation was always acquired in lung adenocarcinoma patients after exposure to EGFR-TKIs' therapies, which related to resistance to the first or second generation of TKIs." (PMID 33997043, 2021). "The stacking model based on 18F-FDG PET/CT images is capable to predict EGFR mutation status of patients with lung adenocarcinoma automatically and non-invasively." (PMID 34367993, 2021). "Here, we present the case of an 81‐year‐old man who was diagnosed with lung adenocarcinoma cStage IVA harboring the uncommon EGFR L861Q mutation." (PMID 33533191, 2021). "In conclusion, we developed a deep learning-based model using 18F-FDG PET/CT images to predict the EGFR mutation status in patients with lung adenocarcinoma." (PMID 34367993, 2021).
lung adenocarcinoma (continued). "Our data demonstrated that WWOX rs73569323 polymorphism is positively associated with tumor size and invasion in patients with EGFR-L858R mutant lung adenocarcinoma." (PMID 34948746, 2021). "Some mutations of common driver genes for lung adenocarcinoma also have been identified in BAs, such as EGFR, KRAS and BRAF." (PMID 34663408, 2021). "Epidermal growth factor receptor tyrosine kinase inhibitors (EGFR-TKIs) are the first-line treatment for patients with lung adenocarcinoma with sensitizing EGFR mutations." (PMID 34689761, 2021). "Overall, immunohistochemistry can be used as an adjunct to the molecular method in identifying the EGFR gene mutations in lung adenocarcinoma." (PMID 34181354, 2021). "EGFR mutated lung adenocarcinomas were predicted to be more sensitive to Erlotinib, Gefitinib, Afatinib and Osimertinib (all with p < 0.0001)." (PMID 34548481, 2021). "Our study descriptively identified the genetic variations of advanced Chinese lung adenocarcinoma patients and analyzed the overall survival of patients with EGFR mutations." (PMID 33997043, 2021). "Targeted NGS analysis helped predict the prognosis and recurrence of patients with resected EGFR-mutation lung adenocarcinoma and benefitted in the identification of patients with a high risk of recurrence for selection for adjuvant EGFR-TKIs treatment." (PMID 34298845, 2021). "Sensitive and resistant EGFR-mutated (EGFRm) lung adenocarcinoma cell models were seeded on the resulting meshes from two different PCL concentrations (10 and 15% w/v), and then several LCSC features were analyzed." (PMID 34771484, 2021). "Restricting variants to putative oncogenic drivers improved model performance in a number of cases, such as predicting EGFR mutation status in lung adenocarcinoma." (PMID 34441338, 2021). "In Taiwan, gefitinib, erlotinib, and afatinib had been reimbursed in first-line treatment for advanced lung adenocarcinoma harboring EGFR mutation in 2011, 2013, and 2014, respectively." (PMID 34434112, 2021). "Another study further supported the superiority of PNA clamping for the detection of EGFR mutation in PF cell blocks from lung adenocarcinoma patients with a low proportion of tumor cells." (PMID 34199799, 2021). "EGFR has been implicated in many other cancer types, including breast, cervical, astrocytoma, bladder, esophageal, gastric, lung adenocarcinoma, colorectal, ovarian, and others." (PMID 34359613, 2021). "ddPCR was performed to detect EGFR exon 21 L858R point mutation (Ex21) and EGFR exon 19 deletion mutation (Ex19) in sputum samples from patients with lung adenocarcinoma." (PMID 33757469, 2021). "Lung adenocarcinoma with MLCs has a high rate of EGFR mutation, and some researchers believe that the MLCs are a predictor for EGFR mutation in lung adenocarcinoma." (PMID 34234879, 2021). "The findings of our present study suggest that rrSCNAs in plasma ctDNA detected before second-line therapy with osimertinib are clinically relevant in patients with advanced EGFR-mutated lung adenocarcinoma." (PMID 33919291, 2021). "Targeted therapy with TKIs is characterized as a standard treatment for patients with EGFR-mutated lung adenocarcinoma." (PMID 34367939, 2021). "The overexpression of ANXA1 was observed in H1650 and H1975 lung adenocarcinoma cells with EGFR mutations (H1650: exon 19 deletion; H1975: L858R + T790M) and A549 lung adenocarcinoma cells wild-type EGFR gene." (PMID 34439260, 2021). "Here, we describe an unusual case of biphasic mesothelioma of the pleura with areas mimicking myxofibrosarcoma concomitant with EGFR-mutated lung adenocarcinoma in a 72-year-old Japanese man." (PMID 34333253, 2021). "Taken together, we report the largest characterization of potential cancer-associated class I immunopeptidome in EGFR-mutant lung adenocarcinoma to date." (PMID 34391887, 2021). "Despite complete resection and adjuvant chemotherapy, the recurrence rate of early EGFR-mutated lung adenocarcinoma remains high." (PMID 34298845, 2021).
lung adenocarcinoma (continued). "EGFR mutations in primary lung adenocarcinoma can be detected with high sensitivity in sputum samples if sputum cytology is positive." (PMID 33757469, 2021). "These mutations are present in nearly a third of all lung adenocarcinomas and predict efficacy to EGFR tyrosine kinase inhibitors (TKIs) such as gefitinib and erlotinib." (PMID 34055528, 2021). "For advanced lung adenocarcinoma patients with common epidermal growth factor receptor (EGFR) mutations (exon 19 deletions or the exon 21 L858R mutation), tyrosine kinase inhibitors (TKIs) are the standard therapies, and achieve favorable responses." (PMID 34178699, 2021). "There was also a similar case with mediastinal lymph node metastasis in this study in which all tumor pathology types were lung adenocarcinoma, but the EGFR mutations were completely different." (PMID 34544453, 2021). "With advances in genomic research and targeted therapy, the therapeutic strategies and prognosis of patients with NSCLC, especially EGFR-mutated lung adenocarcinoma, have been greatly improved." (PMID 33718183, 2021). "Otahal and his team proved that fluvastatin or pitavastatin combined with erlotinib led to apoptosis in human lung adenocarcinoma cells with a mutated or overexpressed epidermal growth factor receptor (EGFR)." (PMID 34959621, 2021). "The case was a 69-year-old woman who underwent surgery in March 201X and was diagnosed positive for EGFR-del19 in lung adenocarcinoma using the commercial diagnostic kit cobas®." (PMID 33863983, 2021). "Epidermal growth factor receptor-tyrosinase kinase inhibitor (EGFR-TKI) resistance is the major obstacle in the treatment of lung adenocarcinoma (LUAD) patients harboring EGFR-sensitive mutations." (PMID 33516270, 2021). "Despite complete resection and adjuvant chemotherapy, the recurrence rate of EGFR-mutated lung adenocarcinoma exceeds expectations, highlighting the need for improved treatment strategies." (PMID 34298845, 2021). "For patients with advanced lung adenocarcinoma and an EGFR mutation, treated with epidermal growth factor receptor-tyrosine kinase inhibitors (EGFR-TKIs), the five-year survival rate is 40–50%." (PMID 34201833, 2021). "In five lung adenocarcinoma patients resistant to later-line osimertinib, recurrent mutations at EGFR L792 and/or L718 were identified using targeted next-generation sequencing of tissue or cell-free DNA from plasma or pleural effusion." (PMID 33937055, 2021). "Epidermal growth factor receptor (EGFR) mutations, mainly exon 19 deletions and L858R exon 21 mutations, are present in about 12% of lung adenocarcinomas tested in France." (PMID 34680280, 2021). "Because of the importance of identifying the EFGR gene mutation, particularly in lung adenocarcinoma, we conducted this study to evaluate immunohistochemistry’s performance in detecting the specific EGFR mutated protein." (PMID 34181354, 2021). "We extended the molecular machinery for EGFR-related signaling in the EGFR-addictive lung adenocarcinoma cells with the sensitive mutation of EGFR (PC9 and H1650 with exon 19 deletion mutation [deletion E746-A750], H3255 with exon 21 L858R)." (PMID 34367939, 2021). "We also analyzed the expression of different proteins implicated in EGFR-driven lung adenocarcinoma." (PMID 34298655, 2021). "For multiple primary lung adenocarcinoma, we should routinely test for EGFR mutations in all lesions." (PMID 34544453, 2021). "All patients were initially diagnosed with lung adenocarcinoma with an EGFR mutation and received first-generation EGFR-TKI treatment." (PMID 33718183, 2021).
lung adenocarcinoma (continued). "Here, we report a case of a long‐term response to afatinib in an elderly patient harboring uncommon EGFR mutation‐positive lung adenocarcinoma." (PMID 33533191, 2021). "Among all lung adenocarcinoma cases, epidermal growth factor receptor (EGFR) mutations account for 47.9% in the Asian population and 45% in the Japanese population." (PMID 33586356, 2021). "The diagnosis of a breast recurrence of lung adenocarcinoma was confirmed by molecular analysis that revealed the presence of the same EGFR mutation detected in the primary lung neoplasia (exon 19, p.E746_A750del c.2236_2250del NM_005228.4)." (PMID 34590588, 2021). "Osimertinib is a tyrosine kinase approved and effective in treating lung adenocarcinomas that have one of several common activating mutations in epidermal growth factor receptor." (PMID 34068720, 2021). "Another small sample study (25 EGFR mutations and 20 wild‐type EGFRs) found that contrast, correlation, and inverse difference moment radiomic features were associated with EGFR mutation status in lung adenocarcinoma." (PMID 33314737, 2021). "Nine patients from Xuanwei with advanced lung adenocarcinoma bearing uncommon EGFR mutations, with a median age of 59 years, started EGFR-TKI treatment." (PMID 33889543, 2021). "EGFR inhibition by Gefitinib causes apoptosis in sensitive constitutively-active EGFR-mutant lung adenocarcinoma cells." (PMID 33976119, 2021). "Nonetheless, in most clinical situations, it is important to appreciate that most lung adenocarcinomas with EGFR mutations are likely to have additional co-existing oncogenic alterations." (PMID 35052732, 2021). "We found that the first-line treatment with osimertinib was safe and resulted in a long-term response in elderly patients with de novo EGFR T790M-mutated lung adenocarcinoma." (PMID 33976888, 2021). "In patients with EGFR-L858R mutant lung adenocarcinoma, WWOX rs3764340 C/G polymorphism is also associated with tumor growth and invasion." (PMID 34948746, 2021). "We conducted genomic test in 152 Chinese patients; in our cohort, the EGFR sensitive mutation rate was significantly higher than those declared in American patients with lung adenocarcinomas (46.05% vs. 19.0%)." (PMID 33997043, 2021). "EGFR signaling is important in driving high regulatory T cell (Treg) infiltration, despite low CD8+ effector T cell infiltration in EGFR‐mutated lung adenocarcinomas, via CCL22 upregulation through JNK/cJun and CXCL10 downregulation mediated by IRF1." (PMID 34096184, 2021). "For patients initially diagnosed with EGFR-mutant advanced lung adenocarcinoma, concurrent brain metastasis was associated with severe morbidity, poor survival outcomes, and quality of life." (PMID 34434112, 2021). "Recent clinical trials of lung adenocarcinoma with immune checkpoint inhibitors revealed that lung adenocarcinoma patients with EGFR mutations have a poor response to immunotherapy." (PMID 34484468, 2021). "Targeted NGS analysis provides information on the prognosis of patients with resected EGFR-mutation lung adenocarcinoma and helps to identify patients with high relapse risks who require intensive chemotherapy or adjuvant EGFR-TKIs treatments." (PMID 34298845, 2021). "Osimertinib treatment also showed clinical benefits in T790M‐negative patients in a study involving 199 lung adenocarcinoma patients diagnosed with EGFR mutations." (PMID 33529490, 2021). "In particular, the third generation anti-EGFR osimertinib is currently recommended for patients with EGFR-mutated lung adenocarcinoma, alectinib, or brigatinib for those harboring ALK rearrangements, and crizotinib for those with ROS1 rearrangement." (PMID 33435440, 2021). "Gefitinib promotes migration and epithelial‐to‐mesenchymal transition of lung adenocarcinoma cells harboring EGFR mutation by enhancing CXCR4 expression." (PMID 34555268, 2021).
lung adenocarcinoma (continued). "The subgroup of lung adenocarcinomas patients with co-occurrence of aberrations in classical therapeutic genes such as EGFR mutation and PD-L1 positive expression accounted for 9.6% of Chinese adenocarcinoma patients." (PMID 35003359, 2021). "A recent study revealed that PTK7 expression is associated with EGFR mutations and plays an oncogenic role in lung adenocarcinomas." (PMID 34367983, 2021). "The prevalence of HER2 amplifications is higher in EGFR-mutated lung adenocarcinoma treated with early generation EGFR TKIs compared to treatment with osimertinib (5% versus 1–2% respectively)." (PMID 34202748, 2021). "In the current study, we analyzed the genetic profiles of 131 patients with stage I–IIIA EGFR-mutated lung adenocarcinoma tumors using targeted NGS." (PMID 34298845, 2021). "In Taiwanese patients with EGFR-mutant lung adenocarcinoma, especially those with EGFR-L858R gene mutation, the underlying mechanism of the WWOX signaling cascade dysregulation is worthy of further exploration." (PMID 34948746, 2021). "Despite the substantial improvement in the treatment of EGFR-mutated lung adenocarcinoma, there remain key issues for clinical practice that motivate ongoing research." (PMID 34202748, 2021). "The EGFR-mutation lung adenocarcinomas were more addictive to EGFR-induced survival signaling than the EGFR-WT lung adenocarcinomas." (PMID 34367939, 2021). "Kirsten rat sarcoma viral oncogene homolog (KRAS) and EGFR are the most frequently mutated oncogenes in human lung adenocarcinoma." (PMID 34200786, 2021). "According to a worldwide prospective study, Asian patients with lung adenocarcinoma showed 51.4% EGFR overall mutation frequency." (PMID 34975346, 2021). "Sputum cell‐free DNA (cfDNA) is a valuable surrogate sample for assessing EGFR‐sensitizing mutations in patients with advanced lung adenocarcinoma." (PMID 33932095, 2021). "The recent prospective study of the West Japan Oncology Group 8114LTR (WJOG8114LTR) evaluated the clinical significance of monitoring ctDNA in 57 patients with advanced lung adenocarcinoma harboring EGFR mutations during afatinib treatment." (PMID 34422670, 2021). "Here, we investigated the risk factors of acquired T790M mutation among patients with lung adenocarcinoma with EGFR mutation who were treated with EGFR‐TKIs." (PMID 33529490, 2021). "Osimertinib can exert antitumor effects on lung adenocarcinoma harboring a T790M mutation by binding to a completely different site of EGFR compared to other EGFR-TKIs." (PMID 34445227, 2021). "Brain metastasis is related to EGFR mutations in patients with lung adenocarcinoma and T790M mutation." (PMID 33529490, 2021). "A recent case study reported that a 72-year-old male lung adenocarcinoma patient with an EGFR deletion mutation initially responded to EGFR-TKI treatment but later developed acquired resistance against EGFR-TKI." (PMID 34503137, 2021). "Our study demonstrated that high Romo1 expression was significantly associated with poor PFS and OS in patients with EGFR-mutant lung adenocarcinoma treated with frontline targeted therapy." (PMID 34956890, 2021). "Another strong point of our study was that it included a homogenous cohort of patients with EGFR-mutated lung adenocarcinoma." (PMID 34298845, 2021).